KRAS (KRas proto-oncogene, GTPase)
Diseases named in the same sentence as KRAS in open-access papers (continued):
Sharing a sentence is not in itself a finding about the gene and the disease.
tumor (continued). "All patients included in the MRR who were treated with panitumumab and concurrent oxaliplatin-containing chemotherapy had confirmed wild-type tumour status, again though a small number (9.9%) were only tested for KRAS mutation status." (PMID 29183279, 2017). "Initially, patients with tumours that had mutations of exon 2 of the KRAS oncogene were found to be resistant to treatment with anti-EGFR mAbs." (PMID 29183279, 2017). "Although FOSL1 inhibition involved the regulation of mitotic genes, sensitivity of mutant KRAS cells to FOSL1 loss seems to occur irrespectively of the proliferative rate of tumour cells." (PMID 28220783, 2017). "NRAS‐mutation(+) CRC significantly correlated with older age, distal colon, more mucinous component of the tumor, and lower lymph vessel invasion when compared with KRAS‐mutation(+) CRC." (PMID 28378457, 2017). "Another particular case was represented by the tumor resistant to gefitinib-afatinib-osimertinib treatment, in which the KRAS-G12D mutation occurred." (PMID 28416737, 2017). "KRAS gene copy number loss in tumor DNA is associated with better treatment response to anti‐EGFR drugs even in the presence of KRAS mutation in the tumor." (PMID 28504856, 2017). "Further, the preclinical spontaneous mouse model of PC suggests that PTEN deficiency, along with oncogenic KRAS, exhibits the pro-metastatic potential of tumor cells." (PMID 28383487, 2017). "The results show that blood sampling offered high sensitivity and specificity which suggests that KRAS mutations can be assayed this way when tumor tissue is inconvenient or unavailable." (PMID 28415658, 2017). "One such effort attempted to quantitate circulating tumor DNA harboring KRAS mutations in patients with refractory CRC receiving panitumumab." (PMID 28981524, 2017). "KRAS mutations are genetic events that occur early in tumor progression and are associated with more aggressive tumor phenotypes and/or resistance to treatment." (PMID 27283493, 2016). "We detected an extraordinary level of tumor heterogeneity, with microclonal (mutant allele fraction <0.10) KRAS, NRAS, FLT3, and/or PTPN11 hotspot mutations evident in 31/57 (54.4%) patients." (PMID 27683039, 2016). "When both tumor components were sequenced together for KRAS (Kirsten rat sarcoma viral oncogene homolog) gene mutations, the resulting pyrogram indicated that it was not a wild type, suggesting that it contained KRAS mutation." (PMID 27597976, 2016). "Determination of KRAS mutations in plasma is based on the presence of circulating tumor DNA (ctDNA) and offers the possibility of constant monitoring without the need for serial biopsies." (PMID 27043547, 2016). "Recently, nanoparticles carrying siRNA targeting GATA2 significantly reduced tumour growth in a xenograft murine model of NSCLC harbouring oncogenic KRAS mutations.These promising results require further exploration." (PMID 27191720, 2016). "The median OS was 10.2 months (95 % CI, 4.9–15.5) in patients with plasma KRAS mutations and 8.4 months (95 % CI, 0.0–22.5) in patients with these mutations in their tumor tissue." (PMID 27519791, 2016). "In the multivariate analysis, we selected sex, age, tumor differentiation, nodal stage, KRAS, BRAF and PIK3CA gene mutations in relation to DFS and OS by stage and in both stages combined together." (PMID 27074743, 2016). "This will not have a noticeable effect on KRAS wild-type tumor cells, but will reduce the stimulatory drive of extracellular TIMP-1 on KRAS mutated tumor cells." (PMID 27509063, 2016). "Of the 289 patients who participated in the randomized phase II study, 208 cases with a known EGFR or KRAS mutation status in their tumor tissues were examined." (PMID 27519791, 2016).
tumor (continued). "In this study we demonstrate that some of the variation in the distribution of KRAS substitutions between tumor types is explained by differences in mutational biases." (PMID 26902163, 2016). "The 24 tumor samples in Cluster-A significantly correlated with the presence of KRAS mutation (P = 1×10-4), and proximal location (P = 3×10-6)." (PMID 27563825, 2016). "We also found a significant mutational enrichment within the tumor-associated transmembrane signal transduction genes KRAS, PTPN21, and USP54 of relapsed patients." (PMID 26527318, 2016). "The effect of tumour mutations in KRAS codons 12 or 13 on the efficacy of necitumumab in combination with mFOLFOX6 was studied in 25 evaluable patients." (PMID 26766738, 2016). "In this regard, the heterogeneity score for the KRAS p.G12C mutation in this tumor was < 50, confirming that only a fraction of neoplastic cells were carrying the mutation." (PMID 27448974, 2016). "In agreement with these previous reports, KRAS mutation was frequently detected in 46 (41%) out of 112 tumor samples." (PMID 27563825, 2016). "Recently a combination of PI3K/MEK inhibition with BKM120 and PD0325901 was effective in inducing tumor regression in mouse model of cancer that harbored a KRAS mutation." (PMID 27623107, 2016). "LOH for the DCC gene, KRAS gene mutation, and microsatellite instability were also evaluated for each tumor, utilizing standard polymerase chain reaction methods." (PMID 26970738, 2016). "Because PTEN deficiency and mutationally-activated KRAS can synergistically co-regulate tumor morphology in transgenic mice, we studied a larger series of 92 KRAS genotyped CRCs (cohort ii) and found CM on low power microscopy in 43% CRCs." (PMID 27119498, 2016). "Three of the discordances involved KRAS mutation in the metastasis, while mutations were detected only in the primary tumor in another patient." (PMID 26968843, 2016). "Among the RAS family, KRAS is one of the most prominent oncogenes due to its ability to transform human cells into malignant tumor cells, particularly when harboring an activating mutation in codon 12 or 1337." (PMID 27857191, 2016). "Four and three studies presented mean tumour size with SD or p value according to KRAS or GNAS mutation, respectively." (PMID 27512631, 2016). "We assembled a panel of CRC organoids carrying either wild-type or mutant RAS, as well as normal organoids and tumor organoids with a CRISPR-introduced oncogenic KRAS mutation." (PMID 27845624, 2016). "Cells carrying KRAS mutations were only detected in a fraction of the tumor biopsies from resistant patients." (PMID 27449290, 2016). "The predominant version of this earliest tumor-promoting mutation is the substitution of Glycine to Aspartic acid at codon 12 (KRAS(G12D))." (PMID 26771140, 2016). "In fact, the allelic frequency of the KRAS mutations in the tumor samples ranged between 2.2% and 79.8%, with mean and median values of 21.58 and 10.65, respectively." (PMID 27448974, 2016). "Accordingly, in March 2008, the protocol for the present study was amended to include evaluation of tumour mutation status at KRAS codons 12 and 13 among enrolled patients." (PMID 26766738, 2016). "The average tumour size of IPMN patients with KRAS mutations ranged from 2.4 to 2.9 cm, whereas the mean size of IPMNs with wild-type KRAS ranged from 2.51 to 2.86 cm." (PMID 27512631, 2016).
tumor (continued). "The median PFS of the patients with plasma KRAS mutations was 1.6 months (95 % CI, 0.1–3.1), a result that was comparable with the PFS of patients with tumor-tissue KRAS mutations (median PFS, 1.8 months [95 % CI, 0.0–3.6])." (PMID 27519791, 2016). "Compared with the EGFR mutation and EML4-ALK rearrangement patients, KRAS mutation patients demonstrated unique features in terms of tumor site, pathology stage and smoking status." (PMID 26739511, 2016). "In summary, the current study highlights a novel role of CXCR2 signaling in mediating KRAS(G12D) mutation-induced autocrine growth transformation of tumor cells by directly modulating the levels of KRAS protein and its downstream signaling." (PMID 26771140, 2016). "This percentage was higher than that of tumours with lower ZEB1 (9 KRAS-mutated tumours in a total of 31 tumours; 29%), but the association between KRAS mutations and ZEB1 expression changes was not statistically significant (Fisher's exact test, P=0.11)." (PMID 27456471, 2016). "Rare somatic variants with frameshift mutations on APC and cetuximab resistance mutation on KRAS were identified in the tumor tissues." (PMID 27121310, 2016). "Only when the two tumor components were tested separately did it become clear that each component harbored a different KRAS mutation." (PMID 27597976, 2016). "IHC staining revealed that RCAN2 was expressed mainly at the tumor IF in tumor cells and that the expression of this gene was repressed by oncogenic mutation of KRAS in human CRC." (PMID 27526107, 2016). "Extended mutation analyses of additional tumour RAS loci (KRAS exons 3 and 4, and NRAS exons 2, 3 and 4) suggested that the efficacy benefit was further restricted to patients with tumours wild type at all screened loci." (PMID 26766738, 2016). "Of the 14 cases, 8/14 (57 %) exhibited KRAS (exon 2, codon 12 or 13) mutations in the primary tumour and 1/14 (7 %) a NRAS (exon 3, codon 61) mutation." (PMID 27756406, 2016). "Consistently, ZEB1 also promoted KRAS-mutated xenograft tumour growth but suppressed EGFR-mutated xenograft tumour growth." (PMID 27456471, 2016). "In one of these cases it was possible to analyze the tumor tissue by ddPCR and the analysis confirmed the presence of the KRAS mutation detected in the ctDNA, although at a very low frequency (case L41: KRAS p.G13D 0.03%)." (PMID 27448974, 2016). "To determine the contribution of mutational biases differences in generating the observed variation in KRAS driver substitution distribution, we wanted to characterize the mutational biases of the three studied tumor types." (PMID 26902163, 2016). "The role of KRAS mutations in acquired TKI resistance was also supported by a recent study demonstrating a high incidence of KRAS mutations in the cell-free circulating tumor DNA from TKI-resistant NSCLC patients." (PMID 27304188, 2016). "KRAS mutations are associated with tumor resistance to EGFR TKIs (erlotinib, gefitinib) and to monoclonal antibody against EGFR (cetuximab)." (PMID 25902737, 2016). "Mutations in the MAPK pathway in the form of activating KRAS mutations occur during tumor progression in the classical path of CRC development." (PMID 27221051, 2016). "Our study showed that decreased cytoplasmic p62 expression was significantly associated with an unfavourable tumour-specific OS, especially in the subgroup of KRAS-mutated CRCs." (PMID 27444698, 2016). "For example, EGFR exon 19 deletions are associated with the tumor susceptibility to EGFR targeted therapy while KRAS mutations are associated with the tumor resistance to EGFR targeted therapy." (PMID 27597976, 2016). "Multiregion analysis was performed in 60 spatially separated tumor areas according to the pathological tumor node metastasis (pTNM) staging and KRAS, NRAS and BRAF mutations were tested using pyrosequencing." (PMID 27916952, 2016).
tumor (continued). "A tumor sample with a new mutation of exon 59 of NRAS oncogene (as present in exon 59 of KRAS oncogene) would therefore produce a low correlation coefficient, allowing the operator to detect this unusual sample." (PMID 27651826, 2016). "KRAS codon 12 or 13 mutations were detected in the tumours from 9 of these 25 patients (36.0%), and the tumours from the remaining 16 patients (64.0%) were wild type at these loci." (PMID 26766738, 2016). "The new panel also identified a KRAS p.G12V mutation in the plasma from a patient that had a KRAS p.G12C mutation in the tumor tissue (case C2)." (PMID 27448974, 2016). "In DNA extracted from fresh-frozen portions of tumor mucosa, the percentage of KRAS G12V mutation relative to wild-type sequences was 36.83% (n = 10, median)." (PMID 27043547, 2016). "In the QUASAR trial, HER2 overexpression was observed in 17 of 811 (2.1%) KRAS/BRAF WT tumours compared with one of 421 (0.2%) tumours harbouring a KRAS or BRAF mutation (p = 0.01)." (PMID 26690310, 2016). "Although all of these chimeric proteins caused the degradation of mutant KRAS and the death of KRAS-mutant-tumor cell lines, the RBD-VIF with a protein transduction domain (PTD), named PTD-RBD-VIF, had the strongest tumor-killing effect." (PMID 27322423, 2016). "The percentage of KRAS G12V mutation relative to wild-type sequences in tumor-derived DNA was also determined." (PMID 27043547, 2016). "Tumours with a CIMP ‘high’ phenotype are thought to arise from sessile serrated adenomas and these tumours carry specific mutations in the BRAF gene reminiscent to those encountered in the KRAS gene in CIN tumours." (PMID 27279102, 2016). "We explored the activity of lenalidomide on tumor neo-vasculature in a patient-derived tumorgraft model generated from a single KRAS-mutated CRC liver metastasis, propagated in mice." (PMID 27149858, 2016). "According to manufacturer’s instructions, the minimal tumor cell percentage in samples for the IdyllaTM KRAS Mutation Assay should be at least 25% to guarantee reliable results." (PMID 27685259, 2016). "We also identified a single sample with a G13D KRAS mutation, intriguingly in a tumor also harboring an NF1 frame-shift mutation." (PMID 27078850, 2016). "This pitfall in diagnosis is based on the assumption that distinct clones of tumor cells exists in solid tumors harboring potential heterogeneity in KRAS mutations." (PMID 27064574, 2016). "During phase I treatment with MK-2206, a pan-AKT inhibitor, a dramatic 23% shrinkage in tumor was found in a patient with a loss of PTEN KRAS-dependent PDAC, which was thought to have occurred via PI3K–AKT–mTOR inhibition." (PMID 27200288, 2016). "In contrast, the frequency of KRAS mutations significantly increased with tumor stage predominantly associated with later stages of adenocarcinoma progression." (PMID 26881969, 2016). "In summary, our results indicate the reliable assessment of KRAS mutation status for therapeutic decisions in pre-therapeutic biopsies as well as in post-therapeutic residual tumor tissue." (PMID 27064574, 2016). "Patient tumor DNA that showed a mutation in exon 2 of the KRAS gene by histological examination showed the same mutation by sequencing in the patient’s EVs DNA." (PMID 27662833, 2016). "One metastasis harbored both PI3KCA and KRAS mutations, while the synchronously sampled primary tumor was mutation free." (PMID 26968843, 2016). "This association is well in line with the previously demonstrated association of KRAS wild-type with high tumour grade and reduced survival in the herein investigated cohort." (PMID 27048364, 2016).
tumor (continued). "Since the mutations of KRAS are early events involved in tumor initiation, HOC-7 provide a good model to explore the connection between ras-raf-MAPKs pathway and NF-kB in tumorgenesis." (PMID 27484466, 2016). "The tumor volume of the KRAS mutation patients were larger than those of the EGFR mutation patients (P < 0.05)." (PMID 26739511, 2016). "The KRAS oncogene is one of the most frequently mutated genes in human cancer, being altered in approximately 20% of all human tumours." (PMID 26881434, 2016). "In all disease stages, but particularly in stage IV, we observed a significant association of HER2 overexpression with KRAS/BRAF WT tumours (p < 0.0001)." (PMID 26690310, 2016). "The concordance of KRAS mutation status between the tumor tissue and plasma was 85.9 % (95 % CI, 80.1–91.8), and it presented a sensitivity of 50.0 % (95 % CI, 41.6–58.4) and a specificity of 89.4 % (95 % CI, 84.2–94.6)." (PMID 27519791, 2016). "We clarified that these miRNAs are up-regulated in both PDAC and IPMN, perhaps reflecting the presence of KRAS gene mutation in those neoplasms." (PMID 27380024, 2016). "Somatic mutations in these genes were detected in 537 of 1284 (41.8 %) primary tumours: 457 (35.6 %) KRAS, 53 (4.1 %) NRAS, and 27 (2.1 %) BRAF mutations." (PMID 27737711, 2016). "Baseline characteristics including age, sex, tumor location, tumor grade, T stage, N stage, synchronous metastasectomy site, and recurrence site were similar between the KRAS wild type and KRAS mutation cohorts." (PMID 26887348, 2016). "KRAS mutations confer drug resistance and lead to aggressive tumor growth and metastasis and a poor clinical outcome." (PMID 26884312, 2016). "We demonstrated that PKCΒ methylation is more frequent in tumours with KRAS mutation (p-value ≤0.04)." (PMID 25366420, 2015). "Molecular and morphologic tumor characteristics, such as KRAS/BRAF mutation status, mismatch repair (MMR) protein expression, tumor growth pattern, and tumor cell budding, have been shown to be of key therapeutic and/or prognostic relevance in CRC." (PMID 26106602, 2015). "We also investigated the prognostic value of cfDNA and analysed the tumour-specific KRAS mutations in the plasma." (PMID 25875772, 2015). "The distribution of observed mutations was consistent with prior reports: 50% (19 of 38 patients) had a KRAS mutant tumor, 16% (6 of 38 patients) had a PIK3CA mutation, 8% (3 of 38 patients) showed a mutation in BRAF, and none showed an EGFR mutation." (PMID 25575824, 2015). "Several studies have shown that for patients with identifiable KRAS mutations in their tumor tissue, the corresponding mutations can be detected in DNA isolated from plasma, and elevated ctDNA levels have been associated with decreased overall 2-year survival." (PMID 25575824, 2015). "Two patients (both at stage II) displayed a KRAS G12S and a G12A mutation by plasma analysis, but were determined as WT by tumor-tissue testing." (PMID 25946211, 2015). "Previously, KRAS has been identified as a possible target for cancer therapeutics, due to its activation driving a number of traits associated with tumor cells, in particular cell growth and proliferation." (PMID 25436011, 2015). "In PDA tumours harbouring wild-type KRAS, we identified BRAF and PIK3CA mutations at oncogenic hotspots expanding the spectrum of oncogenic drivers in PDA." (PMID 25855536, 2015). "Sporadic tumours present a more complicated case whereby consideration must be paid to site-dependence and mutual exclusivity of mutations in the KRAS and BRAF genes and the crosstalk between epigenetics and genetics." (PMID 25622259, 2015). "Paraffin embedded primary tumor tissue was available for 12 of the 31 patients tested for a KRAS mutation in plasma." (PMID 26498594, 2015). "We report for the first time that PTEN loss and KRAS activation promotes cellular persistence, while the combination results in robust tumor formation in vivo." (PMID 26497685, 2015).